BAP1 (BRCA1 associated deubiquitinase 1)
Diseases named in the same sentence as BAP1 in open-access papers (continued):
Sharing a sentence is not in itself a finding about the gene and the disease.
tumor (continued). "Compared to tumours exclusively mutated for PBRM1, tumours with BAP1 only mutation conferred adverse clinicopathological features and prognosis." (PMID 26448938, 2015). "Overexpression of miR-200c, and miR-141, both of which putatively target the BRCA1 associated protein-1 oncosuppressor-encoding BAP1, is correlated with OV tumor growth, dedifferentiation, and invasiveness." (PMID 25875127, 2015). "A BAP1 L65* mutation in this tumor results in a truncation of the BAP1 protein near the amino terminus." (PMID 24931142, 2014). "BAP1 has recently been implicated as an important tumour suppressor protein in a number of different tumour types and found to be one of seven genes whose mutation is the most indicative of poor prognostic outcome." (PMID 24748658, 2014). "NGS performed on a tumor sample from the liver resection obtained at the time of diagnosis revealed BAP1 mutation L65*." (PMID 24931142, 2014). "A low tumor percentage due to the small size of a lesion or small size of the spitzoid component, or the presence of a lot of TILs, can all hamper BAP1 mutation analysis in this setting." (PMID 25593912, 2014). "There have been several cancer types associated with BAP1 germline mutations but the full spectrum of tumor susceptibility is still to be ascertained." (PMID 23977234, 2013). "There has also been an association between amelanotic tumor development and germline BAP1 mutation suggesting a possible phenotypic characteristic of BAP1 mutation carriers." (PMID 23977234, 2013). "Loss of heterozygosity (LOH) of the BAP1 mutation was also observed in DNA from tumor tissue from II:11." (PMID 23977234, 2013). "As evidenced by the literature, there is a large tumor spectrum that appears to accompany BAP1 germline mutation." (PMID 23977234, 2013). "Next, genetic counseling should be offered and germline DNA should be tested for BAP1 mutations to identify individuals and families at higher risk for one or more of the neoplasms associated with the BAP1 cancer syndrome." (PMID 22935333, 2012). "In comparison with the PBRM1 mutation, BAP1-deficient tumours were of higher grade and had distinct gene expression profiles." (PMID 23016578, 2012). "Next, we sought to determine whether the increased tumor growth ability is due to the loss of MHC-II molecules in BAP1-deficient A20 cells." (PMID 39817454, 2025). "Notably, sporadic mutations in BAP1 can occur in UM between 6 months and 5 years of primary tumor initiation (within 2 doublings of the first UM clone) — oftentimes before diagnosis." (PMID 41160198, 2025). "BAP1 loss is associated with higher tumor aggressiveness, metastasis and poor patient survival." (PMID 40754831, 2025). "BAP1 is a tumor suppressor, and its downregulation is linked to the invasiveness of ICC." (PMID 40421086, 2025). "Prognostic factors include clinical features like tumor size (especially > 1 cm for nodular lesions), ulceration, and neck lymphadenopathy, as well as histological features like Ki67 expression, BAP1 loss, heparanase expression, and potentially depth of invasion." (PMID 40344340, 2025). "The BAP1 mutation was associated with rapid tumor progression and a stronger response to JX-594." (PMID 40856833, 2025). "Tumor inhibition by BRCA1-associated protein 1 (BAP1) could be achieved in part by inhibiting SLC7A11 and thereby promoting ferroptosis." (PMID 40498062, 2025). "Commonly, inactivating mutations in BAP1, which are seen in a wide variety of tumour types, produce protein truncations with loss of its nuclear localization signal, which sequesters the protein in the cytoplasm, although complete gene deletions or missense mutations are also observed." (PMID 39976080, 2025).
tumor (continued). "Loss of BAP1 expression, which often occurs alongside partial deletion of chromosome 3, is strongly associated with a high risk of metastasis and poor survival rates due to a highly aggressive tumour." (PMID 40361330, 2025). "Indeed, the BAP1 p.T310T fraction (43%) was nearly identical to the expected number of cells carrying the mutation (based on the estimated fraction of 60% tumor cells in sampled tissue)." (PMID 40600748, 2025). "Other studies have linked BAP1 loss to a more inflammatory tumor microenvironment, which could support improved immunotherapeutic response." (PMID 41561288, 2025). "Indeed, BAP1 is the cancer gene most frequently associated with poor patient survival across many common tumor types." (PMID 40754831, 2025). "BAP1 mutations are attributed to enhanced aggressiveness of the tumor and poor survival." (PMID 41479787, 2025). "Furthermore, according to preclinical studies, BAP1 loss is associated with an inflammatory tumor phenotype, potentially acting as a favorable biomarker for immunotherapy responsiveness." (PMID 41463268, 2025). "We have previously shown that ccRCC tumors can be classified into those with mutually exclusive mutations in BAP1 (and associated with high tumor grade, activation of mTORC1 and poor patient survival) and mutations in PBRM1 (and associated with better prognosis)." (PMID 40754831, 2025). "In the genomic analysis of the primary tumor tissue of the TRACERx Renal study, the multi-region sequencing underscores intratumoral heterogeneity and validates clonal mutual exclusivity patterns associated with BAP1 and PBRM1/SETD2." (PMID 41440218, 2025). "Our results indicate that JX-594 suppressed BAP1-deficient tumor growth through IRF7-dependent IFN-β induction; reactivating this pathway may be a novel therapeutic strategy for RCC." (PMID 40856833, 2025). "This may result in paucicellular or heterogeneous samples when employing a microinvasive approach and possibly depend on tumour characteristics such as chronicity, thickness, and mutations such as BAP1 loss." (PMID 40759490, 2025). "One tumour in our series lacked the epithelioid morphology characteristic of BIMs, despite showing loss of BAP1 by IHC; this tumour was notable for DPN‐like (with diffuse expression of HMB‐45 and nuclear β‐catenin by IHC) and conventional nevus‐like (yet BAP1‐inactivated) components." (PMID 39976080, 2025). "Furthermore, it was demonstrated that M2 macrophages were associated with these exhausted T-cyt cells, which, in turn, are linked to mutations in BAP1 within tumor cells." (PMID 39751643, 2025). "By inhibiting the acetylation of histones, these agents may reverse the effects of BAP1 loss, leading to a less aggressive tumour, and potentially restoring normal gene expression." (PMID 40361330, 2025). "FGFR2 fusions and IDH1 mutations predict response to targeted inhibitors; MSI-H/dMMR status, PD-L1 positivity, and high tumor mutational burden correlate with improved immunotherapy outcomes; and BAP1 or BRCA1/2 alterations indicate sensitivity to PARP inhibition." (PMID 41226789, 2025). "Moreover, BAP1 mutations are associated with an immunogenic tumor microenvironment and with alteration of tumor antigen presentation, making tumors with BAP1 loss good candidates for immunotherapy." (PMID 40361508, 2025). "BAP1 is a tumor suppressor gene located on chromosome 3p21 and is mutated in 47% of primary UM." (PMID 40177537, 2025).
tumor (continued). "In addition, a few histone PTMs displayed changes linked to increasing tumor stage or associated with the BAP1 mutation status." (PMID 38349785, 2024). "In this regard, BAP1 has emerged as a critical tumor suppressor gene across multiple cancer types whose mutations predispose to tumor development that might be relevant in RM." (PMID 38785832, 2024). "Additionally, they found that the spread of UM to other parts of the body is linked to the deletion of BAP1 in the original tumor." (PMID 39596556, 2024). "Recent studies have clarified the diagnostic significance of BAP1 loss in select tumor types." (PMID 38708315, 2024). "Overall, LF2 may represent the relationship between EMT in the renal epithelial cells and TME, a phenomenon particularly pronounced in ccRCC tumours with BAP1 mutations." (PMID 39592856, 2024). "Tumour growth inhibition potential was significantly increased in BAP1-deficient xenografts." (PMID 38519707, 2024). "In addition, tumour weight of BAP1-deficient xenografts treated with the combination were also lower as compared to single-agent-treated xenografts." (PMID 38519707, 2024). "This suggests that in MPeM, the loss of BAP1 may correlate with tumor infiltration by various immune cell types, including CD8+ T cells, Tregs, macrophages, and DCs." (PMID 38994676, 2024). "The tumor suppressor BAP1 encodes a nuclear deubiquitinating enzyme, which is in the form of a polycomb-repressive deubiquitinase (PR-DUB) complex to reduce the ubiquitination of histone 2A (H2A) in nucleosomes, so as to perform epigenetic regulation gene expression." (PMID 38475936, 2024). "Mutation of BAP1 abrogates the tumor repressive ability and may contribute to the progression of uveal melanoma and renal cell carcinoma." (PMID 38908072, 2024). "Moreover, mutations in BAP1, a recognized tumor suppressor, substantially enhance the development of metastases by inactivating the protein, and the prognosis is severe." (PMID 39596556, 2024). "Thus, MP65 seems to be more representative of a BAP1-mutated tumor than MP38 (which harbors isodisomy)." (PMID 38349785, 2024). "Since LF2 along with LF1 and LF5 levels were associated with patient overall survival, we generated Cox Proportional-Hazards models to evaluate how they compared to existing models of patient prognosis based on tumour stage, grade and somatic mutations (BAP1, SETD2, and PBRM1) (Table EV8)." (PMID 39592856, 2024). "In addition, mutations in the tumour suppressors BAP1, PBRM1 and SETD2, which co-localise with VHL on chromosome 3p and are frequently disrupted in ccRCC, suppress ISGF3-mediated ISG expression." (PMID 39282259, 2024). "CTF1 and RAPGEF3 were previously reported to be parts of gene signatures related to tumor microenvironment and immune system, with the first seen downregulated and methylated in BAP1 mutated samples; PALMD was found to have low expression in metastatic UM tissues, and GSTA3 in low-survival patients." (PMID 38339073, 2024). "However, the germline mutation of BAP1 is widely found in many cancers and makes tumor cells lose the vulnerability to ferroptosis, which is considered as an important susceptibility factor of hereditary cancers." (PMID 38475936, 2024). "The complexity of cell-cell interactions in the tumor microenvironment may trigger the invasion and migration of tumor cells with monosomy 3 and BAP1 deficiency." (PMID 39056751, 2024). "Since the change of lactate levels has a profound impact on immune cell behavior, it remains to be illustrated that, to what extent, BAP1 loss could cause immune evasion of tumor cells through the modulation of acidity in tumor microenvironment." (PMID 39587076, 2024). "Loss of BAP1 expression is associated with an increased density of tumor-infiltrating lymphocytes and tumor-associated macrophages, which may be involved in immune suppression." (PMID 37272766, 2023). "Our finding of high CD8 + TIL counts in a BAP1-mutated tumor confirms and extends previous results." (PMID 36562826, 2023).
tumor (continued). "Herein, we set out to investigate whether BAP1 mutations could regulate the development in UM, and our results demonstrated that BAP1 mutations could induce the tumor immune microenvironment in UM by inactivating the NF-κB signaling pathway." (PMID 37710185, 2023). "However, only a single BAP1 GPV was identified in 131 cases (0.7%) in an individual with a family history of BAP1- associated tumours." (PMID 37607989, 2023). "Previous analyses of tumors and blood from the PEMDAC trial suggested that genetics (BAP1 status or a UV mutational signature), tumor burden (levels of ctDNA and LDH), and immune cell distribution (T cells, monocytes, and neutrophils) were associated with responses and survival." (PMID 37377898, 2023). "KN-93 significantly suppressed the tumor growth in mice xenografted with BAP1-deficient MMe cells." (PMID 37479714, 2023). "BAP1 (BRCA1-associated protein-1) is a ubiquitin carboxy-terminal hydrolase that has been shown to be a multifunctional tumor suppressor gene and is involved in cellular metabolism and DNA repair by regulating gluconeogenesis via PGC1 stabilization, suppressing mitochondrial respiration." (PMID 37272766, 2023). "This should include analysing the mitotic phenotypes of BAP1-deficient cells in which BRCA1 expression is restored, as well as testing whether tumour cells undergoing mitotic progression are especially sensitive to loss of BAP1." (PMID 36550359, 2023). "Furthermore, converse to the supervised discriminant analyses, the LOOCV approach does not show differences in metabolite patterns between patients harboring a BAP1 or EIF1AX-mutated tumor in the merged dataset." (PMID 36982149, 2023). "The overall lifetime risk for at least one BAP1-associated tumour is up to 85%." (PMID 37607989, 2023). "BRCA1-associated protein-1 (BAP1) is a recognised tumour suppressor gene." (PMID 37607989, 2023). "To compare the impact of the loss of tumour suppressors in vitro relative to in‐patient samples, we performed differential expression analysis to calculate fold‐changes in gene expression in BAP1 WT vs BAP1 mutant patients." (PMID 36740402, 2023). "A current understanding of the sequence of molecular events in a growing, metastasizing UM is that mutations in the Gq/11 pathway are necessary for clonal expansion of tumour cells, whereas near‐mutually exclusive mutations in BAP1, SF3B1 or EIF1AX confer malignant and metastatic potential." (PMID 35801361, 2023). "We recently confirmed the association between a high histologic tumour pigmentation and a lower survival rate in the Leiden enucleation group and showed a link between high levels of pigmentation and loss of chromosome 3/loss of expression of the BAP1 gene." (PMID 37240204, 2023). "However, high expression of PD-1 and programmed cell death-ligand 1 (PD-L1) and the presence of tumor-infiltrating lymphocytes are associated with parameters for poor prognosis, such as loss of BAP-1, the epithelioid cell type, and liver metastasis." (PMID 37237550, 2023). "Inactivating mutations and deletions of 3 tumour suppressor loci, namely CDKN2A/B, NF2, and BAP1 predominate, with functional loss of each tumour suppressor occurring in over 50% of cases and single or combinatorial loss of the 3 loci found in all possible permutations." (PMID 37441092, 2023).
tumor (continued). "Notably, upregulation of argininosuccinate 1 synthase (ASS1), an enzyme essential for cellular synthesis of arginine and its downstream metabolites, was identified in BAP1w-/KO cells and in BAP1-deficient MPM cells or tumor samples." (PMID 36669126, 2023). "BRCA-associated protein 1 (BAP1) is a tumor suppressor, with histone deubiquitinase activity which contributes to the formation of the Polycomb repressive complex PR-DUB, a molecular machinery involved in chromatin rearrangement and inhibition of cell proliferation." (PMID 37887570, 2023). "We found that CAMK2D/BAP1-DKO reduced cell proliferation, strongly suggesting that CAMK2D might play a critical role in the tumor growth of BAP1-deficient MMe cells." (PMID 37479714, 2023). "We hypothesized that some of these genes, epigenetically repressed due to BAP1 loss, may have tumor-suppressive properties." (PMID 36657447, 2023). "For example, histone deacetylase and enhancer of Zeste 2 Polycomb repressive complex 2 are upregulated in BAP1-deficient tumors; therefore, targeting these genes could improve BAP1-deficient tumor sensitivity to treatment." (PMID 35425712, 2022). "It has also been shown that loss of BAP1 may lead to myeloid transformation in vivo, suggesting that BAP1 may function as a tumor suppressor in the hematopoietic system." (PMID 35194152, 2022). "And as also demonstrated in this study, the prognostic implication cannot be explained by differences in patient age, tumor size, ciliary body involvement, extraocular extension, BAP-1 expression, in diagnostic procedures or in management of the included patients." (PMID 36310339, 2022). "In addition, tumor tissue sequencing identified a concurrent somatic variant in BAP1 (partial deletion of exon 12) and a low tumor mutational burden." (PMID 35381901, 2022). "The LUAD tumor tissue carried the germline BAP1 variant with a VAF of 21.2% (coverage 500×)." (PMID 35885614, 2022). "Furthermore, BRCA1-Associated Protein 1 (BAP1) on chromosome 3p was identified as a novel tumor-driver gene in ccRCC using extensive parallel sequencing techniques." (PMID 35425712, 2022). "In addition, somatic BAP1 mutation was found in 3 tumors (18.8%) and 1 tumor (6.2%) had a SF3B1 mutation." (PMID 35267470, 2022). "Additional driver mutations in PBRM1, SETD2, and BAP1 may occur, and the number of driver events is significantly associated with tumor stage, grade, and presence of necrosis." (PMID 35463327, 2022). "Furthermore, SLC7A11 overexpression or treatment with ferroptosis inhibitors has been shown to partly overcome the tumor growth suppression caused by BAP1 restoration in tumors." (PMID 35280777, 2022). "Therefore, depletion of MBD6 leads to a global loss of BAP1 occupancy at the chromatin, resulting in a reduction of BAP1-dependent gene expression and tumor growth in vitro and in vivo." (PMID 36180891, 2022). "It is unclear whether mutation of BAP1 can lead to the recruitment of more immune cells into the tumor microenvironment and thus affect the prognosis of HCC." (PMID 34976173, 2022).